NAGK (N-acetylglucosamine kinase)
Description:
Converts endogenous N-acetylglucosamine (GlcNAc), a major component of complex carbohydrates, from lysosomal degradation or nutritional sources into GlcNAc 6-phosphate. Involved in the N-glycolylneuraminic acid (Neu5Gc) degradation pathway: although human is not able to catalyze formation of Neu5Gc due to the inactive CMAHP enzyme, Neu5Gc is present in food and must be degraded. Also has N-acetylmannosamine (ManNAc) kinase activity (By similarity). Also involved in innate immunity by promoting detection of bacterial peptidoglycan by NOD2: acts by catalyzing phosphorylation of muramyl dipeptide (MDP), a fragment of bacterial peptidoglycan, to generate 6-O-phospho-muramyl dipeptide, which acts as a direct ligand for NOD2.
Synonyms: GNK; HSA242910
Tractability: Small molecule: a structure with a bound ligand is known; it has a high-quality binding pocket. PROTAC: ubiquitination databases record sites on it; its protein half-life has been measured.
Target class: Enzyme; Transferase
Gene: Protein-coding gene on chromosome 2 (71,064,344 to 71,079,808, forward strand). Ensembl gene ENSG00000124357.
Subcellular location (Human Protein Atlas): Cytosol; Nucleoplasm
Pathways (Reactome):
Metabolism of proteins: Synthesis of UDP-N-acetyl-glucosamine
Gene Ontology:
Molecular function: muramyl dipeptide kinase activity; N-acetylglucosamine kinase activity; protein binding; N-acylmannosamine kinase activity
Biological process: defense response to bacterium; N-acetylglucosamine catabolic process; positive regulation of nucleotide-binding oligomerization domain containing 2 signaling pathway; response to muramyl dipeptide; UDP-N-acetylglucosamine biosynthetic process; N-acetylglucosamine metabolic process; N-acetylmannosamine metabolic process; N-acetylneuraminate catabolic process
Cellular component: extracellular exosome; cytosol
Genetic constraint (gnomAD): Loss-of-function variants: 35 observed, 43.28 expected, observed/expected ratio (o/e) 0.81, 90% interval 0.62 to 1.07. The upper end of that interval is the gene's LOEUF score, 1.07, which puts it in group 4 of 6, group 1 being the genes least tolerant of losing a copy. Missense variants: 446 observed, 459.23 expected, observed/expected ratio (o/e) 0.97, 90% interval 0.9 to 1.05. Synonymous variants: 172 observed, 180.67 expected, observed/expected ratio (o/e) 0.95, 90% interval 0.84 to 1.08.
Homologues: Orthologues: chimpanzee NAGK (99% identical), macaque NAGK (98% identical), rabbit NAGK (94% identical), rat Nagk (92% identical), dog NAGK (92% identical), mouse Nagk (92% identical), guinea pig NAGK (87% identical), pig NAGK (67% identical), tropical clawed frog nagk (65% identical), zebrafish nagk (61% identical), Drosophila melanogaster Nagk (44% identical), Caenorhabditis elegans W06B4.2 (29% identical), and 1 more.
Diseases named in the same sentence as NAGK in open-access papers:
NAGK is named in the same sentence as 22 diseases in open-access papers, as found by Europe PMC text mining. Sharing a sentence is not in itself a finding about the gene and the disease. The quoted sentences say what the papers report.
neuroblastoma (2 papers, 2017 to 2020). Neuroblastoma (NB) is the most common solid, extracranial childhood tumor. "We analyzed ALK copy numbers relative to NAGK copy numbers using ddPCR of gDNA from our neuroblastoma cell line panel." (PMID 29156716, 2017).
pancreatic ductal adenocarcinoma (2 papers, 2024). An infiltrating adenocarcinoma that arises from the epithelial cells of the pancreas. "This appears to be cancer specific as previously it has been shown NAGK expression is enhanced in pancreatic ductal adenocarcinoma and blocking NAGK leads to cancer cell death." (PMID 38601153, 2024). "Deletion of NAGK increases de novo hexosamine biosynthesis; conversely, glutamine deprivation inhibits de novo HBP but triggers the NAGK-dependent salvage pathway in pancreatic ductal adenocarcinoma (PDAC), suggesting that cross-talk occurs between the salvage and de novo HBP." (PMID 38510444, 2024).
asthenozoospermia (1 paper, 2021). "Moreover, N-acetyl glucosamine kinase (NAGK) was predicted to significantly affect ATP production and regulate metabolism in asthenozoospermia." (PMID 34344298, 2021).
breast carcinoma (1 paper, 2019). "Other notable genes decreased by SK1 KD were NDUFA2 in prostate and E2F5, NAGK, VAPB, NFATC3, CDK2 in breast cancer cell lines." (PMID 30971929, 2019).
COVID-19 (1 paper, 2024). A disease caused by infection with severe acute respiratory syndrome coronavirus 2. "Clinical trials could explore targeted therapies that enhance NAGK function or modulate the NOD2 pathway, aiming to improve outcomes in MS patients with COVID-19." (PMID 39493765, 2024).
lung adenocarcinoma (1 paper, 2024). A carcinoma that arises from the lung and is characterized by the presence of malignant glandular epithelial cells. "Our study identified germline variants affecting lung adenocarcinoma patient survival, possibly due to a regulatory role on gene expression, in particular of NT5DC2 and NAGK genes." (PMID 39409885, 2024). "Nonetheless, we found that, in lung adenocarcinoma tissue, NAGK (N-acetylglucosamine kinase) expression levels are associated with overall survival." (PMID 39409885, 2024). "High NT5DC2 and NAGK expression in lung adenocarcinoma tissue was already shown to correlate with poor overall survival." (PMID 39409885, 2024).
melanoma (1 paper, 2023). A malignant, usually aggressive tumor composed of atypical, neoplastic melanocytes. "To elucidate dynein-mediated microtubule transport, we used a melanoma cell line to observe the colocalization of NAGK or SNRPN protein transport with melanosome." (PMID 37511433, 2023). "To describe NAGK–SNRPN complex variability in the cell body and process of the neuron, we observed the microtubule transport machinery of NAGK and SNRPN in a melanoma cell line model." (PMID 37511433, 2023).
ovarian tumors (1 paper, 2013). "The potential candidate biomarkers screened in ovarian tumors found to be significantly upregulated in comparison to normal tissues were: protein phosphatase-1, ferritin light chain, proteasome R-6 and NAGK (N-acetylglucosamine kinase)." (PMID 23591842, 2013).
pancreatic cancer (1 paper, 2024). "In separate studies of pancreatic cancer, knockout of N-acetylglucosamine kinase (NAGK) had no appreciable effect on cell growth under nutrient-replete culture conditions, but renders these cells unable to grow in a mouse model." (PMID 40603611, 2024).
proteinopathies (1 paper, 2020). "We previously showed N-acetylglucosamine kinase (NAGK) promotes dynein functionality and suggested this might promote aggregate removal and effectively address proteinopathies." (PMID 32796833, 2020).
viral infections (1 paper, 2021). "A three-gene transcript signature, comprising HERC6, IGF1R, and NAGK, was derived from the discovery cohort of 56 participants with bacterial infections and 27 with viral infections." (PMID 34423323, 2021).
tumor (6 papers, 2020 to 2024). "The MYCN copy number and NAGK (reference gene) copy number (M/N) ratio in plasma and corresponding tumor tissues of NB patients was detected using an economical, sensitive, and specific single‐tube dual RT‐PCR approach developed in this study." (PMID 35892165, 2023). "In order to accurately quantify the MYCN copy number in plasma and tumor tissue of NB patients, the N‐acetylglucosamine kinase gene (NAGK) was selected as the internal reference gene." (PMID 35892165, 2023). "We then studied the role of NAGK in tumor growth in vivo by injecting NAGK CRISPR KO cells into the flank of NCr nude mice." (PMID 34844667, 2021). "Further investigation will be needed to elucidate the physiological functions of NAGK, as well as the mechanisms through which it supports tumor growth and its potential role in modulating therapeutic responses." (PMID 34844667, 2021). "Together, these data identify an important role for NAGK-dependent hexosamine salvage in supporting PDA tumor growth." (PMID 34844667, 2021). "NAGK expression is elevated in human PDA tumors, and NAGK deficiency suppresses GlcNAc salvage in cells and tumor growth in mice." (PMID 34844667, 2021). "Of note, initial tumor growth was comparable between control and KO cells, but the NAGK knockout tumors either stopped growing or shrank while control tumors continued to grow larger." (PMID 34844667, 2021). "From analysis of publicly available microarray data and gene expression data from the Cancer Genome Atlas (TCGA), we indeed found NAGK expression to be increased in tumor tissue relative to adjacent normal regions of the pancreas or to pancreas GTEx data." (PMID 34844667, 2021). "In this study, we investigated the impact of nutrient deprivation on the HBP and glycosylation in PDA cells, identifying a key role for hexosamine salvage through the enzyme N-acetylglucosamine kinase (NAGK) in PDA tumor growth." (PMID 34844667, 2021). "Other than the powerful performance of MYCN/NAGK ratio prediction, higher plasma MYCN/NAGK ratio showed consistent with heavier tumor load." (PMID 32896084, 2020). "NAGK expression is increased in human PDA tumors and NAGK knockout reduces tumor growth in vivo." (PMID 34844667, 2021). "Interestingly, KO tumor samples showed increased L-PHA signal, indicating that NAGK deficiency results in altered glycosylation within tumors." (PMID 34844667, 2021). "Indeed, a recent study demonstrated that NAGK knockout in PDA impairs tumor growth in vivo, while only exhibiting a modest impact on cellular proliferation in vitro." (PMID 34951587, 2021). "High plasma MYCN/NAGK ratio predicting MYCN amplification status of tumor." (PMID 32896084, 2020). "In our study, the most concern is whether plasma MYCN/NAGK ratio could evaluate amplified MYCN of NB tumor accurately." (PMID 32896084, 2020). "Combined with other clinical features, plasma MYCN/NAGK ratio could successfully distinguish heavier tumor burden, insufficient treatment, and poor prognosis." (PMID 32896084, 2020). "In conclusion, plasma MYCN/NAGK ratio may be a promising indicator of MYCN amplification of tumor in NB." (PMID 32896084, 2020). "Beyond the threshold of 6.965, the MYCN/NAGK ratio correlated with a heavier tumor burden." (PMID 32896084, 2020). "Our manuscript and the Kimet al.’s manuscript together indicate that NAGK may take on a heightened importance in the context of high GlcNAc availability and nutrient deprivation, a situation that is likely to occur within the tumor microenvironment." (PMID 34844667, 2021). "Thus, the higher plasma MYCN/NAGK ratio indicated heavier tumor burden in NB patients." (PMID 32896084, 2020). "(C) Final tumor volume and (D) final tumor weight of subcutaneous tumors generated from PANC-1 NAGK knockout cells in vivo." (PMID 34844667, 2021). "In sum, we report a key role for NAGK in feeding UDP-GlcNAc pools in PDA cells and in supporting xenograft tumor growth." (PMID 34844667, 2021).
tumor (continued). "NAGK expression is elevated in human PDA, and NAGK deletion from PDA cells impairs tumor growth in mice." (PMID 34844667, 2021). "According to the FISH results of tumor MYCN status, plasma MYCN/NAGK ratio was significantly higher in MYCN‐positive patients with NB than in negative patients, 69.07 (median CI 95%, 53.39, 142.50) vs 1.27 (median CI 95%, 1.00, 1.53)." (PMID 32896084, 2020). "In a cellular model of cancer different from lung (i.e., pancreatic), knocking down NAGK limited tumor growth, since the absence of this gene did not allow for a quick recycling of UDP-GlcNAc." (PMID 39409885, 2024). "Final tumor volume and weight were markedly reduced in the absence of NAGK." (PMID 34844667, 2021). "More importantly, plasma MYCN/NAGK ratio is a promising, noninvasive, less time‐consuming, and repeatable method to check MYCN amplification of tumors in NB when tumor tissues are limited and MYCN nonamplification is detected in bone marrow cells by FISH test." (PMID 32896084, 2020).
cancer (4 papers, 2021 to 2024). A tumor composed of atypical neoplastic, often pleomorphic cells that invade other tissues. "Next steps will include examining the role of NAGK in healthy cells and testing whether it could be targeted for cancer treatment." (PMID 34844667, 2021). "However, NAGK’s roles in physiology and cancer biology have been minimally studied." (PMID 34844667, 2021). "Cancer cells that lacked NAGK formed smaller tumors, suggesting that the cells grow more slowly because they cannot recycle UDP-GlcNAc fast enough." (PMID 34844667, 2021).
neurodevelopmental disorder (1 paper, 2021). A behavioral and cognitive disorder with onset during the developmental period that involves impaired or aberrant development of intellectual, motor, or social functions. "We hope these findings will direct future studies to gain more insight into the role of these variants in the loss of NAGK function and their role in neurodevelopmental disorders." (PMID 34360815, 2021).
NAGK also shares sentences with these, for which no sentence is quoted: bacterial infection (2 papers); infection (2); adenocarcinoma (1); adenovirus infection (1); GNE myopathy (1); idiopathic inflammatory myopathies (1); multiple sclerosis (1); systemic candidiasis (1).